KIF12 (kinesin family member 12)
Description:
Involved in the negative regulation of fatty acid biosynthesis, probably acting as an adapter that allows ubiquitination of acetyl-CoA carboxylase 1 (ACACA) by E3 ubiquitin-protein ligase COP1, and promotes ACACA degradation. The adapter function requires the C-terminal proline-rich domain and may be apart from the kinesin motor activity (Probable).
Synonyms: PFIC8
Gene: Protein-coding gene on chromosome 9 (114,086,126 to 114,099,292, reverse strand). Ensembl gene ENSG00000136883.
Subcellular location: Cytoplasm, cytoskeleton; Cell projection, cilium
Subcellular location (Human Protein Atlas): Mid piece; Nucleoplasm; Principal piece
Pathways (Reactome):
Hemostasis: Kinesins
Vesicle-mediated transport: COPI-dependent Golgi-to-ER retrograde traffic
Genetic constraint (gnomAD): Loss-of-function variants: 79 observed, 86.11 expected, observed/expected ratio (o/e) 0.92, 90% interval 0.76 to 1.11. The upper end of that interval is the gene's LOEUF score, 1.11, which puts it in group 4 of 6, group 1 being the genes least tolerant of losing a copy. Missense variants: 819 observed, 835.08 expected, observed/expected ratio (o/e) 0.98, 90% interval 0.93 to 1.04. Synonymous variants: 353 observed, 336.61 expected, observed/expected ratio (o/e) 1.05, 90% interval 0.96 to 1.14.
Homologues: Orthologues: chimpanzee KIF12 (99% identical), macaque KIF12 (96% identical), pig KIF12 (88% identical), dog KIF12 (87% identical), rabbit KIF12 (83% identical), mouse Kif12 (80% identical), rat Kif12 (80% identical), guinea pig KIF12 (63% identical), Drosophila melanogaster Klp54D (32% identical). Paralogues in human: KIF13A (28% identical), KIF13B (27% identical), KIF1A (27% identical), KIF1C (27% identical), KIF7 (27% identical), KIF1B (26% identical), KIF3B (26% identical), KIF21A (26% identical), KIF21B (26% identical), KIF16B (25% identical), KIF17 (25% identical), KIF27 (25% identical), and 29 more.
Diseases named in the same sentence as KIF12 in open-access papers:
KIF12 is named in the same sentence as 42 diseases in open-access papers, as found by Europe PMC text mining. Sharing a sentence is not in itself a finding about the gene and the disease. The quoted sentences say what the papers report.
cholestasis (5 papers, 2022 to 2025). Impairment of the bile flow caused by obstruction within the liver, or outside the liver in the bile duct system. "In previous studies, the human liver disease accompanying KIF12 mutations have been simply described as ‘cholestasis’." (PMID 39920308, 2025). "In addition, human KIF12 mutations have been described in inherited inflammatory liver disease and cholestasis." (PMID 39920308, 2025). "We report three familial early-onset liver cirrhosis pedigrees with homozygous KIF12 mutations, accompanying MASH-like steatosis and cholestasis." (PMID 39920308, 2025). "PFIC8 follows autosomal recessive inheritance, and KIF12 mutations cause cholestasis by changes in hepatocyte polarity." (PMID 35884482, 2022). "Although the cholestasis according to KIF12 mutation can be progressive, this KIF12 mutation from Patient 2 may monogenetically and primarily cause a MASH/MAFLD-like liver steatosis preceding the onset of apparent cholestasis." (PMID 39920308, 2025). "However, our detailed investigations in KIF12-defective human and mouse revealed that MASH should also occur in the upstream or in parallel to the development of cholestasis." (PMID 39920308, 2025). "Recent studies detected biallelic mutations of KIF12 in children with high GGT and cholestasis without extrahepatic abnormalities, suggesting a role in the pathogenesis of cholestatic liver disease." (PMID 36830709, 2023).
renal cystic disease (4 papers, 2015 to 2023). "KIF12 encodes a protein involved in the control of cell division and its downregulation leads to the abnormal planar cell polarity observed in cystic kidney disease." (PMID 36830709, 2023). "While KIF12 has been implicated as a disease severity modifier of renal cystic disease via HNF-1B-induced transcription, its potential role in PRCA etiology is not immediately clear." (PMID 29156765, 2017). "Together, these data provide genetic and informatic validation of the predicted renal cystic disease-modulating effects of Mpkd1-3 loci and implicate Kif12 as the candidate locus for Mpkd2." (PMID 26295839, 2015). "Since the protein product of Cys1 localizes to primary cilium together with most genes involved in renal cystic disease, localization of the Kif12 protein product to primary cilia provides further support for this gene as an Mpkd2 locus candidate." (PMID 26295839, 2015). "Additional supporting evidence implicating Kif12 as the Mpkd2 modifier gene candidate is provided by recent studies that demonstrate renal cystic disease-attenuating effects of Kif3a deletion in Pkd1 and Pkd2 mouse models." (PMID 26295839, 2015). "In the current study, we use congenic strain analyses to fine-map the predicted renal cystic disease-modulating effects of the Mpkd loci and provide further supportive evidence implicating Kif12 as the candidate Mpkd2 locus based upon genetic, informatic, and immunolocalization analyses." (PMID 26295839, 2015).
Cholestatic liver disease (3 papers, 2023 to 2024). "Previous cases described pathogenic KIF12 variants as a potential cause for cholestatic liver disease." (PMID 38495495, 2024). "Moreover, these new drugs already applied to other types of PFIC and cholestatic liver disease, could be considered in children and adults with KIF12 and HNF1B defective function." (PMID 36672242, 2023).
breast carcinoma (2 papers, 2016 to 2020). "Similar results were also previously reported on the association between taxane resistance in basal-like breast cancer and kinesins, including KIF3C, KIF5A and KIF12." (PMID 27128470, 2016).
polycystic kidney disease (2 papers, 2023 to 2024). A usually autosomal dominant and less frequently autosomal recessive genetic disorder characterized by the presence of numerous cysts in the kidneys leading to end-stage renal failure. "Further studies have shown that KIF12 may be involved in the development of polycystic kidney disease." (PMID 36830709, 2023).
progressive familial intrahepatic cholestasis (2 papers, 2022 to 2023). Progressive familial intrahepatic cholestasis (PFIC) refers to a heterogeneous group of autosomal recessive disorders of childhood that disrupt bile formation and present with cholestasis of hepatocellular origin. "Among them, within the new classification of progressive familial intrahepatic cholestasis (PFIC), KIF12 pathogenic variants have been included as driving mutations responsible for PFIC-8." (PMID 36672242, 2023).
adenoma (1 paper, 2025). A neoplasm arising from the epithelium. "Time series analysis using the likelihood ratios showed differences in expression of genes including Fos, Lama3, Aldh1a3, Col7a1 and Doks associated with increased induction by t = 12 h, whereas E2f8, Exo1, Clspn, Kif14 and Kif12 all were decreased in Smad4+/+ adenomas." (PMID 40348815, 2025).
autosomal recessive polycystic kidney disease (1 paper, 2023). An inherited disorder characterized by the development of cysts affecting the collecting ducts. "Our results are similar to previous studies in mouse models that implicated Kif12 as a strong candidate positional gene for the major effect modifier 2 (Mpkd2) of autosomal recessive polycystic kidney disease (ARPKD) in mice." (PMID 36830709, 2023).
biliary cirrhosis (1 paper, 2021). "Other high GGT putative cholangio-ciliopathies caused by mutations in Kinesin family member 12 (KIF12), and protein phosphatase 1F (PPM1F) also have histopathologic features suggestive of biliary cirrhosis ± paucity of bile ducts and liver fibrosis." (PMID 33853651, 2021).
ciliopathy (1 paper, 2015). A genetic disorder of the cellular cilia or the cilia anchoring structures, the basal bodies, or of ciliary function. "In addition, KIF12 variants may modulate the severity of a broader spectrum of hepato-renal fibrocystic disorders or even trigger a ciliopathy such as KIF7 mutation-induced Joubert syndrome." (PMID 26295839, 2015).
Cirrhosis (1 paper, 2025). A chronic disorder of the liver in which liver tissue becomes scarred and is partially replaced by regenerative nodules and fibrotic tissue resulting in loss of liver function. "This study shows that a point mutation in KIF12 kinesin is associated with liver steatosis and cirrhosis in human patients and is linked to disruption of ACC1 turnover." (PMID 39920308, 2025). "The kinesin KIF12 protects against liver steatosis and cirrhosis by promoting the ubiquitination and degradation of two lipogenic enzymes: ACC1 and PC." (PMID 39920308, 2025).
dementia (1 paper, 2025). Loss of intellectual abilities interfering with an individual's social and occupational functions. "The studies have compared plasma peptides and proteins in dementia patients with normal controls and found that KIF12 protein peptide is observed more frequently in dementia patients." (PMID 40964093, 2025).
differentiated thyroid carcinoma (1 paper, 2024). Differentiated thyroid carcinoma (DTC), also known as papillary or follicular thyroid carcinoma, is a slow-growing malignancy usually presenting in adults as an asymptomatic thyroid mass. "On the basis of data in the TCGA database, we found the potential role of KIF-12 as a tumour suppressor gene in differentiated thyroid carcinoma, and KIF-12 expression was an independent prognostic factor for thyroid cancer." (PMID 38495495, 2024). "The results showed that the downregulation of KIF-12 expression enhances the progression of differentiated thyroid carcinoma, and the effect may be more significant among younger female patients with unifocal PTC showing lymph node metastasis and BRAF mutation." (PMID 38495495, 2024).
liver cirrhosis (1 paper, 2025). "In the course of whole exome sequencing of early-onset familial liver cirrhosis patients in Israel, we identified the following three human cases from consanguineous marriage carrying bi-allelic KIF12 mutations." (PMID 39920308, 2025). "We identify KIF12 bi-allelic mutations in three inherited early-onset human liver cirrhosis pedigrees, one of which has been mimicked by mouse molecular genetics." (PMID 39920308, 2025).
liver steatosis (1 paper, 2025). "This suggests that KIF12 not only suppresses de novo neutral lipid biosynthesis but also augments the fatty acid oxidation in the liver, as its relevant mechanism against liver steatosis." (PMID 39920308, 2025).
lymph node metastasis (1 paper, 2024). "The prognostic value of KIF12 was also successfully validated in clinical samples from twenty-nine PTC patients with lateral lymph node metastasis by comparison with twenty-two PTC patients without lymph node metastasis (P = 0.004)." (PMID 38495495, 2024). "Finally, the prognostic value of KIF12 was validated by means of clinical samples from PTC patients with and without lateral lymph node metastasis." (PMID 38495495, 2024).
metabolic syndrome (1 paper, 2025). A cluster of metabolic risk factors for CARDIOVASCULAR DISEASES and TYPE 2 DIABETES MELLITUS. "To investigate the relationship between metabolic syndrome and KIF12-mediated liver pathogenesis, we loaded oleic acid to HepG2 cells and assessed the possible changes in KIF12 expression both at protein and mRNA levels." (PMID 39920308, 2025).
overnutrition (1 paper, 2025). An imbalanced nutritional status resulting from excessive intake of nutrients. "Because KIF12 protein tended to decrease by oleic acid loading to HepG2 cells, this mechanism may be partly involved in overnutrition-based MASH/MAFLD pathogenesis." (PMID 39920308, 2025). "The reason of this discrepancy between the protein and mRNA levels is elusive, while the high rate of KIF12 protein turnover implied that an unknown modulation mechanism of KIF12 protein turnover is involved in this overnutrition-induced reduction of KIF12 protein." (PMID 39920308, 2025).
pancreatic cancer (1 paper, 2018). "KIF12 is expressed in fetal liver, adult brain and pancreatic islets, as well as renal tumors, and pancreatic cancer." (PMID 30212457, 2018).
steatosis (1 paper, 2025). Increased lipid within the cytoplasm of cells. "In addition, KIF12-deficient HepG2 cells revealed significant steatosis." (PMID 39920308, 2025). "Furthermore, KIF12-deficient HepG2 cells exhibited significant steatosis, which was ameliorated by overexpressing a proline-rich domain (PRD) of KIF12." (PMID 39920308, 2025). "We have shown that KIF12-PRD within this C-terminal domain directly accelerates the turnover of ACC1 and PC and prevents steatosis in hepatocytes." (PMID 39920308, 2025). "The lipid droplet levels of KIF12-KD cells were reduced to the control level (Fig. EV5D,H), suggesting that ACC1 could be a relevant effector of KIF12-mediated anti-steatosis pathway." (PMID 39920308, 2025).
thyroid cancer (1 paper, 2024). "In conclusion, our study explored the prognostic role of KIF-12 in thyroid cancer for the first time." (PMID 38495495, 2024). "Collectively, our findings indicate that KIF-12 is a promising prognostic suppressor of thyroid cancer." (PMID 38495495, 2024). "Although the prognostic value of KIF-12 in thyroid cancer has been demonstrated in our study for the first time, there were still some limitations in our work." (PMID 38495495, 2024). "On the basis of integrated bioinformatics analyses of data in TCGA database, we also conducted further validation experiments in clinical cases to further confirm that low KIF-12 expression was correlated with the progression and prognosis of thyroid cancer." (PMID 38495495, 2024). "This is the first study to report KIF-12 as a prognostic factor for thyroid cancer." (PMID 38495495, 2024). "GSEA was conducted to better understand the potential function of KIF-12 in thyroid cancer." (PMID 38495495, 2024). "Furthermore, to understand the molecular mechanism of KIF-12 in thyroid cancer, GO and KEGG functional enrichment analysis were performed on the DEGs." (PMID 38495495, 2024). "GSEA demonstrated that gene signatures were linked to the metabolic functions of amine-derived hormones, the TFF pathway and transporter disorders, which may provide some hints for interactions of KIF-12 on thyroid cancer development and progression." (PMID 38495495, 2024). "Materials and Methods: We extracted the clinicopathological data of 502 PTC patients from The Cancer Genome Atlas-Thyroid Cancer (TCGA-THCA) dataset to identify reliable differentially expressed genes (DEGs) between high and low KIF12 expression groups." (PMID 38495495, 2024). "Second, the underlying mechanisms regarding KIF-12 actions are not well investigated, further mechanistic study to assess the impact of KIF-12 on thyroid cancer are needed." (PMID 38495495, 2024).
tumor (4 papers, 2023 to 2024). "This suggests the potential role of KIF-12 as a tumour-suppressing gene in PTC." (PMID 38495495, 2024). "KIF-12 expression was significantly lower in tumour specimens than in normal control specimens." (PMID 38495495, 2024). "Its function in tumours has not been reported, and only a part of the KIF12 function is understood." (PMID 38495495, 2024).
infection (1 paper, 2016). The state of being infected such as from the introduction of a foreign agent such as serum, vaccine, antigenic substance or organism. "However, the expression of Pkd2, Pkhd1, Kif12, Cadherin16 and Socs3, which are known as HNF-1β target genes, did not change (data not shown), and only a few genes, including NR1H4, MITF, SLC3A1, and SLCO4C1, were significantly upregulated 9 h after Ad-HNF1B infection." (PMID 27196561, 2016).
metabolic disease (1 paper, 2025). A congenital disorder (due to inherited enzyme abnormality) or acquired (due to failure of a metabolically important organ) disorder resulting from an abnormal metabolic process. "The discovery of this nano-scale regulation mediated by KIF12 kinesin will therefore accelerate the elucidation of anti-MASH molecular machinery, and stimulate next-generation translational research into kinesins on the regulation of refractory metabolic diseases." (PMID 39920308, 2025).
phenotype (1 paper, 2023). The observable form taken by some character (or group of characters) in an individual or an organism, excluding pathology and disease. "It is believed that KIF12 modulates the expression severity of recessive homozygous biliary phenotype disease in humans." (PMID 36830709, 2023).
KIF12 also shares sentences with these, for which no sentence is quoted: acute liver failure (1 paper); Alagille syndrome (1); cancer (1); COVID-19 (1); cryptogenic cirrhosis (1); cystic fibrosis (1); diabetes mellitus (1); glioma (1); Joubert syndrome (1); kidney disease (1); liver disease (1); liver fibrosis (1); Papillary Thyroid Carcinoma (1); primary sclerosing cholangitis (1); renal cysts and diabetes syndrome (1); schizophrenia 1 (1); thyroid gland disorder (1).